AFP (alpha fetoprotein)
Diseases named in the same sentence as AFP in open-access papers (continued):
Sharing a sentence is not in itself a finding about the gene and the disease.
tumor (continued). "The Risk Estimation of Tumour Recurrence After Transplant (RETREAT) score—comprising AFP at LT, MVI, and the sum of the largest viable tumour diameter and number—is the most widely validated post-LT tool." (PMID 41301037, 2025). "Tumor markers showed elevated lactate dehydrogenase (LDH) and beta-human chorionic gonadotropin (bHCG), along with normal alpha-fetoprotein (AFP)." (PMID 40166779, 2025). "Traditionally, model construction mainly involved clinical and tumor indicators, including Child–Pugh grade, BCLC stage, and AFP." (PMID 39838412, 2025). "Conversely, progesterone receptor (PR) was negative in the only tested case, as well as GATA-3, SALL-4, PTEN, PAX-2, AFP and calretinin, while ARID1A was retained in one case and another tumor has a CK7+/CK20− phenotype." (PMID 39996865, 2025). "Single tumor markers, including PIVKA-II and AFP, showed comparable predictive accuracy to selected multivariable models in post-LT recurrence prediction." (PMID 40656560, 2025). "At transplantation, AFP should be recorded, MVI assessed in the explant, and viable tumour burden documented as inputs to the RETREAT or mRETREAT score." (PMID 41301037, 2025). "Serum tumor markers revealed elevated lactate dehydrogenase (LDH) and mildly elevated alpha-fetoprotein (AFP), while beta-hCG was undetectable." (PMID 41040788, 2025). "After the first round of TILA-TACE, significant differences in the CRR were observed according to alpha-fetoprotein (AFP) level, Eastern Cooperative Oncology Group (ECOG) performance status, tumor size, and CNLC stage." (PMID 40887482, 2025). "Initial univariate analysis showed that AFP levels, CR, Milan criteria, and BCLC stage were all significant predictors of tumor progression." (PMID 41245224, 2025). "Biosensors can detect tumor markers, including CEA, AFP, PSA, CA 19-9, and CA 125 at ultra-low concentrations, e.g., pg/mL or even fg/mL." (PMID 40723883, 2025). "This corresponds to the different expression of tumor serum markers, including LDH, β-hCG, and AFP, in SE and n-SE." (PMID 40750949, 2025). "Results showed that all VIF values were below the threshold of 10, with specific values as follows: AFP (VIF = 3.21), CD147 (VIF = 2.89), IL-6 (VIF = 3.57), capsule integrity (VIF = 1.82), tumor size (VIF = 2.11), and CAR (VIF = 2.98)." (PMID 40919145, 2025). "Single-cell RNA sequencing (scRNA-seq) validated immunological similarity, with lymphocytes and AFP+ and GPC3+ tumour cells in WD-DEN and WD-CCl4 mice having similar correlation coefficients to humans with MASH-HCC." (PMID 40739358, 2025). "Tumor markers, including β-human chorionic gonadotropin (β-HCG) and alpha-fetoprotein (AFP), were within normal limits." (PMID 41220968, 2025). "Patients who continued sorafenib > 6 months had lower AFP, HVT, adverse effects and better tumor response after 3 months." (PMID 40579411, 2025). "Preoperative evaluations included liver function tests (LFTs), serum alpha-fetoprotein (AFP) levels, and imaging for tumor staging and liver volume." (PMID 40206916, 2025). "Meanwhile, tumor maximum diameter, ECOG PS, ALT, AFP level, and sADC were independent predictors of OS in patients." (PMID 41137952, 2025). "In terms of the primary endpoint (i.e., OS), subgroup analysis was performed according to a series of clinical parameters, including region, Child–Pugh class, AFP level, etiology (HBV or HCV infection), tumor number, and tumor size." (PMID 40703528, 2025). "AFP is specifically increased in patients with HCC, and high levels are prognostic of tumor dedifferentiation and poorer survival." (PMID 40722778, 2025). "The patient’s tumor markers, such as carcinoembryonic antigen (CEA), alpha - fetoprotein (AFP), and cancer antigen 125 (CA125), were all determined to be within the normal reference range." (PMID 40308572, 2025).
tumor (continued). "Laboratory workup revealed elevated testosterone, androstenedione, oestradiol, and cortisol levels, while tumour markers (cancer antigen 125 (CA-125), lactate dehydrogenase (LDH), alpha-fetoprotein (AFP)) were within normal limits." (PMID 40918777, 2025). "The statistically significant differences observed between seminomatous and non-seminomatous tumors in terms of serum marker levels affirmed the clinical utility of AFP and β-HCG in distinguishing tumor types." (PMID 41527642, 2025). "In the SR cohort, maximum tumor size, INR, and AFP, albumin, PIVKA-II, and sodium levels were key factors (eFigure 1 in Supplement 1)." (PMID 40960824, 2025). "Serum AFP, AFU, and CEA levels were significantly elevated in the HCC group, reflecting tumor progression." (PMID 40439888, 2025). "Univariable Cox analysis demonstrated that OS was significantly associated with age, the Child–Pugh score, the alpha-fetoprotein (AFP) level, the BCLC stage, the tumor size, PVTT, metastasis, aspartate aminotransferase (AST), and treatment." (PMID 41267980, 2025). "Additionally, interpretation of serum tumor markers is complicated during pregnancy because certain markers (for example, beta-human chorionic gonadotropin (β-hCG) and, less commonly, alpha-fetoprotein (AFP)) are affected by gestation and by concurrent maternal-fetal processes." (PMID 41384202, 2025). "Mainly for serum β-HCG, AFP, and LDH detection, these serum tumor markers are important for treatment, follow-up, and prognosis." (PMID 40559781, 2025). "Tumor markers, such as carcinoembryonic antigen (CEA) and alpha-fetoprotein (AFP), were within normal ranges." (PMID 40517679, 2025). "Univariate analysis showed that AFP level ≥ 60 ng/mL (p < 0.001), DCP value ≥ 100 mAU/mL (p = 0.016), tumor size ≥ 30 mm (p = 0.003), peCTC ≥ 5 (p < 0.001), and poCTC ≥ 5 (p < 0.001) were associated with microscopic PVI." (PMID 40924249, 2025). "Univariate analysis demonstrated that six characteristics correlated with OS, including BCLC stage, presence of distant metastasis, maximum tumor diameter, TACE times, and alpha-fetoprotein (AFP) level." (PMID 40678062, 2025). "Tumor markers, including cancer antigen 125 (CA125), human epididymis protein 4 (HE4), alpha-fetoprotein (AFP), and carcinoembryonic antigen (CEA), were all within normal ranges." (PMID 40150506, 2025). "Laboratory investigations demonstrated normal tumor marker levels, including CA-125, CA-19-9, CEA, AFP, and SCC antigen." (PMID 41459358, 2025). "In the crude cohort, univariate analyses identified several variables as potential predictors of RFS, including age, mALBI grade 2b or 3, multiple nodules, tumor diameter ≥4 cm, presence of MVI, serum AFP ≥100 ng/mL, and serum DCP ≥100 mAU/mL." (PMID 40879478, 2025). "Several high-risk predictors for tumor recurrence and RFS were identified, including age, tumor number, tumor differentiation, preoperative PNI, preoperative SII, postoperative AFP level, and postoperative PIVKA-II level." (PMID 40808940, 2025). "The levels of tumor markers, including cancer antigen (CA)-125, carcinoembryonic antigen (CEA), alpha-fetoprotein (AFP), and beta-human chorionic gonadotropin (beta-hCG) were within normal limits." (PMID 38993381, 2024). "In conclusion, for patients with HCC treated with RT, a nomogram constructed with T stage, N stage, M stage, max tumor size, MVI, AFP, and chemotherapy has good survival prediction ability." (PMID 39286027, 2024). "The study found that high AFP levels correlate with the expression of ANGPTL6, a protein that promotes angiogenesis and tumor progression by activating the ERK1/2 and AKT signaling pathways." (PMID 39685591, 2024). "Tumor markers like carcinoembryonic antigen (CEA), alpha-fetoprotein (AFP), and Cancer Antigen-125 (CA-125) were all within normal limits." (PMID 38826607, 2024). "Immunohistochemistry staining showed the tumor tissues displayed typical HCC features, including the expression of GPC3 and AFP." (PMID 38653754, 2024).
tumor (continued). "The analysis revealed that the non-zero coefficients corresponded to T stage, N stage, M stage, tumor size, MVI, AFP, and chemotherapy in the training group." (PMID 39286027, 2024). "Numerous studies have demonstrated several high‐risk factors for postoperative recurrence and survival, including large tumor size, multiple tumors or satellite foci, tumor envelope invasion or absence, MVI, and high AFP levels." (PMID 38488487, 2024). "Specifically, AFP level, Milan criteria, PVTT, MVI, maximal tumor diameter, and American Joint Committee on Cancer (AJCC) stage were correlated with RFS or OS in all the three HCC‐LT cohorts by univariate Cox regression analysis (log‐rank test, P < 0.05)." (PMID 38498682, 2024). "Alpha-fetoprotein (AFP) and des-gamma-carboxy prothrombin (DCP) are classical tumor markers in clinical practice." (PMID 39321197, 2024). "In the diagnosis of HCC, alpha-fetoprotein (AFP) is detected as a classical tumor marker in most patients with HCC, but low expression of AFP in some patients with HCC is detrimental to the detection of HCC by AFP." (PMID 39617822, 2024). "AFP is the most widely used tumor marker for HCC, which is known to be related to tumor growth and antitumor immunity." (PMID 39289234, 2024). "This study demonstrated that alpha-fetoprotein ≥5.0 ng/ml, ALBI grade ≥2, tumor number ≥3, and maximal tumor size ≥5 cm were significant risk factors for 2-year recurrence-free survival (RFS) in the resection group." (PMID 38768461, 2024). "Patients who had high levels of SNHGs expression were inclined to have larger tumor size, multiple tumors, worse histologic grades, more advanced tumor stage, positive lymphatic metastasis, vein invasion, PVTT, and AFP values >400ug/L." (PMID 38634194, 2024). "All serum tumor markers, including carbohydrate antigen 12-5 (CA12-5), CA19-9, alpha-fetoprotein (AFP), human epididymis protein 4 (HE4), and carcinoembryonic antigen (CEA), were within normal limits." (PMID 39188684, 2024). "They then categorized patients into those with elevated pre-operative tumor markers (B-HCG, AFP, and LDH) and those with normal pre-operative tumor markers." (PMID 39465013, 2024). "In the SEER training cohort, 13 prognostic factors—age, sex, T stage, N stage, M stage, histological or clinical grade, tumor number, max tumor size, MVI, AFP, fibrosis, chemotherapy, and surgery—were evaluated through univariate Cox regression analyses." (PMID 39286027, 2024). "In this study, preoperative tumor marker tests were conducted on 6 patients, including CA125, CA199, CEA, AFP, and HE4." (PMID 38968462, 2024). "Based on the results of univariate analysis, BCLC-stage, CNLC-stage, Child-Pugh score, tumor size, tumor number, tumor burden score, tumor extent, tumor capsule, types of PVI, bone meta, ascites, and AFP were correlated with OS (p < 0.05)." (PMID 38448905, 2024). "AFP is a widely used serum tumor indicator in clinical HCC diagnosis, and previous studies have confirmed that AFP can promote cancer cell proliferation, motility, invasive growth, and metastasis in various HCC cell lines or animal models." (PMID 38488487, 2024). "Significant correlations were observed between cicr_0003570 levels and tumor size, differentiation, microvascular invasion, HCC stage, and serum AFP levels." (PMID 39596302, 2024). "RNA sequencing demarcated tumor models from normal liver cells by displaying high levels of the HB markers GPC3, AFP and IGF2, the proliferation marker Ki67, and the Wnt signaling target AXIN2." (PMID 39529166, 2024). "Considerable efforts are being made to target the overexpressed AFP, CD133, GPC3, and MUC1 antigens on HCC tumour cell surface (NCT05003895 and NCT02587689)." (PMID 38760445, 2024). "The results from the univariate analysis indicated that HBV infection, a tumor diameter ≥3 cm, an ALBI grade 2 or above, an AFP concentration ≥ 400 ng/mL, and early recurrence significantly impacted OS (p < .05)." (PMID 38488487, 2024).
tumor (continued). "In DEN-CCl4 HCC mice the majority of animals showed an iRGD-induced increase of the blood AFP level, whereas in TGFα/c-myc mice this was only found in a portion of the HCC mice, probably due to AFP expression only in a portion of HCCs in this tumour model." (PMID 38889481, 2024). "Six variables were included in the prognostic models based on their clinical relevance: age, maximum tumor diameter, lymph node status, aspartate aminotransferase (AST) level, total bilirubin (TBIL) level, and alpha-fetoprotein (AFP) level." (PMID 38429725, 2024). "Five parameters, log AFP, ALB, Log TBLT, major tumor size, and intrahepatic lesion number, were assessed and identified as predictors and used in model construction." (PMID 38434985, 2024). "After PSM, the balance was improved for most variables, with SMDs reduced to acceptable levels (<0.1) for key covariates, including largest tumor size (SMD = 0.029) and alpha-fetoprotein (AFP, SMD = 0.051)." (PMID 39902133, 2024). "The tumor biomarkers, including neuron-specific enolase (NSE), alpha-fetoprotein (AFP), cancer antigen 19-9 (CA19–9), and cytokeratin 19 fragment (Cyfra21–1), were all negative." (PMID 39104535, 2024). "IMPDH2 upregulation was also found to be associated with key clinical-pathological features, including pre-chemotherapy alpha-fetoprotein (AFP) levels, presence of preoperative metastasis, and the pre-treatment extent of tumor (PRETEXT) staging system." (PMID 39085725, 2024). "The tumor responded to therapy as indicated by standard clinical measures, and the CTC burden dropped to 0.2 cells/mL and AFP to 10.5." (PMID 38727682, 2024). "A nomogram constructed with T stage, N stage, M stage, max tumor size, MVI, AFP, and chemotherapy has good survival prediction ability, for patients with HCC who had received RT." (PMID 39286027, 2024). "Univariate regression analysis indicated a significant correlation between tumor number, tumor size, tumor stage, BCLC stage, AFP, and the expression of KLRB1 on CD8+ T cells and NK cells with patient recurrence and death." (PMID 38914941, 2024). "In terms of LT, a low expression of OGA is thought to promote tumor recurrence of HCC after LT, especially in patients with low levels of alpha-fetoprotein (AFP)." (PMID 38786029, 2024). "The 1960s saw the discovery of AFP and CEA, two tumor biomarkers that are still widely employed as tumor biomarkers." (PMID 38763973, 2024). "Preoperative serum tumor marker tests were conducted on 6 patients, including CA125, CA199, CEA, AFP, and HE4." (PMID 38968462, 2024). "Literature also identifies tumor characteristics as prognostic for RFS, including high alpha-fetoprotein (AFP) levels, satellite nodules and insufficient resection margins." (PMID 38829544, 2024). "In this study, 13 clinical characteristics were considered for LASSO regression analysis: age, sex, T stage, N stage, M stage, histological or clinical grade, tumor number, tumor size, MVI, AFP, fibrosis, chemotherapy, and surgery." (PMID 39286027, 2024). "The nomogram included six variables: age, maximum tumor diameter, lymph node status, AST level, TBIL level, and AFP level." (PMID 38429725, 2024). "Some studies have shown that AFP level, inflammatory indexes, and gadoxetic acid–enhanced magnetic resonance imaging (EOB-MRI) features (tumor diameter and tumor margin) have a close relationship with MVI." (PMID 39090609, 2024). "In 16% of our patients, we observed elevated tumor markers (CEA, AFP, Ca 19–9, or PSA) or abnormalities in the imaging studies, particularly in chest X-ray examinations." (PMID 39459488, 2024). "Another study reported that positive variables included the AFP, PIVIK-II and tumor size, which were used for prediction of MVI through a machine learning model in China." (PMID 39336451, 2024). "The tumor cells show positive staining for CK8/18, CK7, CK19, GS, CK, EMA, CAM5.2, and vimentin; however, they are harmful to alpha-fetoprotein (AFP), Glypican-3, HMB45, SMA, MealanA, and hepatocyte." (PMID 38277577, 2024).
tumor (continued). "The significant variables were T stage, N stage, M stage, tumor number, max tumor size, grade, MVI, AFP, fibrosis, and chemotherapy." (PMID 39286027, 2024). "In contrast, the immunohistochemical markers for testicular malignancies vary widely depending on the tumor type, with placental alkaline phosphate (PALP), AFP, and beta-human chorionic gonadotropin (β-HCG) being the most frequently used markers." (PMID 39735020, 2024). "All tumor markers, including beta human chorionic gonadotropin (β-HCG), serum alpha fetoprotein (AFP), carcinoembryonic antigen (CEA), and carbohydrate antigen 19-9 (CA 19-9), were within normal limits." (PMID 39421548, 2024). "We found that tumor growth was significantly inhibited by AFP-TCR-T transferring, while AFP-TCR-T transferred with IL-21 showed more powerful antitumor capacity than without IL-21." (PMID 38643203, 2024). "We recorded patient age, serum markers [serum alpha-fetoprotein (AFP), human chorionic gonadotropin], and tumor ultrasonic findings (maximum diameter, ultrasonic echo, blood flow signal)." (PMID 39606696, 2024). "Normal liver cells and tumor cells clusters were extracted for separate UMAP clustering and further classified by AFP, PTPRC, ALB, GPC3." (PMID 39015573, 2024). "Beside tumor size, the AFP (alpha-fetoprotein) score is widely applied to assess postoperative prognosis as it correlates with vascular invasion and differentiation in HCC." (PMID 38589847, 2024). "Elevated serum alpha-fetoprotein (AFP) levels, beta-human chorionic gonadotropin (β-hCG), and CA-125 tumor markers provided additional clues." (PMID 39050234, 2024). "Data on patient demographics, recurrence rates, survival times, and tumor marker levels (CEA, CA 19-9, CA 125, AFP, and CRP to albumin ratio (CAR)), disease-free survival duration (DFS), and overall survival durations (OS) were collected and analyzed." (PMID 39371828, 2024). "Six variables have been integrated into this prognostic model: age, maximum tumor diameter, lymph node status, aspartate aminotransferase (AST), total bilirubin (TB), and alpha-fetoprotein (AFP)." (PMID 38673030, 2024). "AFP and DCP serve as ideal surrogates for the tumor’s biological behavior, with higher levels typically signifying worse malignancy in HCC, irrespective of the tumor’s morphological burden." (PMID 38903723, 2024). "The univariate analysis demonstrated that AFP, AST, and tumor diameter were significant CR factors for discriminating the ER and NER groups in the training cohort (all P < 0.05)." (PMID 39582540, 2024). "For patients who have been treated with RT, a nomogram constructed with T stage, N stage, M stage, tumor size, MVI, AFP, and chemotherapy has good survival prediction ability." (PMID 39286027, 2024). "Tumor marker examination (CEA, AFP, CA125, CA19-9, CA15-3 and CA72-4) between malignant GWT and benign GWT were not different (P = 0.344, 0.204, 0.556, 0.661, 0.393 and 0.612, respectively)." (PMID 38191513, 2024). "Other serum tumor markers including carcinoembryonic antigen (CEA), chromogranin A, and Alpha Fetoprotein (AFP) were within normal limits." (PMID 39876872, 2024). "In individuals with persistent HBV infection, PIVKA-II can be utilized as a tumor marker to identify HCC early on, particularly when combined with AFP." (PMID 39859975, 2024). "There were no abnormalities in liver function, kidney function, electrolytes, and serum tumor markers relating to the gastrointestinal and hepatobiliary tract (CEA, AFP, and CA19-9)." (PMID 39099693, 2024). "In our cohort, HCC with an incomplete ITC tended to exhibit more malignant characteristics, as indicated by AFP levels > 400 ng/mL, an NLR ≥ 2.80, a tumor size > 5 cm, poor tumor differentiation, and positive MVI." (PMID 38256485, 2024). "Tumor markers, including carcinoembryonic antigen (CEA), cancer antigen 125 (CA125), and alpha-fetoprotein (AFP), were also within normal limits." (PMID 39834936, 2024).